HOTAIR (HOX transcript antisense RNA)
Diseases named in the same sentence as HOTAIR in open-access papers (continued):
Sharing a sentence is not in itself a finding about the gene and the disease.
tumor (continued). "In OSCC, a significant negative correlation between HOTAIR and E-cadherin expression levels is found in both tumor tissues and cell lines." (PMID 33123473, 2020). "HOTAIR expression is induced by increased H3K4me3 and BRD4 binding to the novel HOTAIR-N promoter in BC cells attached to ECM, suggesting its main role in ECM organization and tumor invasion pathway signaling." (PMID 31072041, 2019). "ADQ specifically bound the 36G46A site in the 5′ functional domain of HOTAIR and efficiently disrupted the interaction between HOTAIR and EZH2 both in vitro and in orthotopic tumor mouse models, thereby reducing the H3K27-mediated tri-methylation of NLK and consequently inhibiting tumor metastasis." (PMID 30764859, 2019). "Significantly higher HOTAIR transcripts were observed in tumors of patients with lymph node and distal metastases, compared to patients without tumor metastasis." (PMID 30813594, 2019). "In addition, HOTAIR also regulates the expression of P27, CylinD1 and CDK4 to promote the transition of tumor cells from G1 phase to S phase to inhibit the apoptosis through non-epigenetic mechanism or other indirect regulatory mechanisms." (PMID 31882666, 2019). "An upregulation in the expression of ANRIL and HOTAIR by IDET may be a compensatory mechanism in response to the suppressed expression of other oncogenic lncRNAs and upregulation of tumor suppressor lncRNAs." (PMID 31784542, 2019). "Examples include the lncRNAs H19, HOTAIR (HOX transcript antisense RNA), and UCA1 (urothelial cancer associated 1, non-protein coding), which silence tumor suppressor genes." (PMID 29983835, 2018). "HOTAIR accumulation down-regulates E-cadherin expression via recruiting EZH2 and H3K27me3 to the E-cadherin promoter, and thus increases OSCC cell motility, favoring tumor cell migration and invasion." (PMID 29416703, 2018). "Previous research has found that the expression levels of FAL1, HOTAIR, LOC100507661, NEAT1, NONHSAT076754 are increased, while GASS-AS1, NAMA, NONHSAT037832 are decreased in tumor tissues, which could be indicators for diagnosis." (PMID 29416703, 2018). "It was reported that HOTAIR was significantly upregulated in cisplatin-resistant NSCLC cells both in vitro and in vivo, and it could enhance tumor cell proliferation, influence G0/G1 cell-cycle arrest, and decrease tumor cell apoptosis." (PMID 28978188, 2017). "In the low-grade tumor area, ISH and IHC detected only slight levels of HOTAIR and IGFBP2." (PMID 28931862, 2017). "Some lncRNAs, such as HOTAIR, H19, NEAT1, HNF1A-AS, ANRIL, are reported to be oncogenic molecules in NPC, while GAS and MEG3 lncRNAs act as tumor suppressors." (PMID 28467811, 2017). "Higher levels of HOTAIR and IGFBP2 were detected in the high-grade tumor area." (PMID 28931862, 2017). "For instance, MALAT-1, HOTAIR, H19, GAS5, UCA1, and GHET1 could regulate the critical pathways of oncogenic and tumor suppression." (PMID 29299179, 2017). "In that study, HOTAIR was expressed at significantly higher levels in HCC tumor compared to adjacent non-cancerous tissue and was an independent prognostic factor for predicting HCC recurrence in liver transplantation patients." (PMID 30159431, 2017). "Additionally, lncRNA growth-arrest-specific 5 (GAS5) plays tumor-suppressive roles in PC cells, whereas NEAT1, MALAT1, HOTTIP and HOTAIR exert oncogenic roles in PC cells." (PMID 29137412, 2017). "HOTAIR expression is higher in OSCC tumor tissue than in paired normal tissue, and high HOTAIR expression always indicates a relatively poor OS or disease-free survival (DFS)." (PMID 27802187, 2017). "HOTAIR expression was greater in tumours with nodal metastasis compared with non-nodal metastatic tumours." (PMID 27323817, 2016). "In addition, lncRNA BANCR exerts tumor-suppressive functions in NSCLC cells, while HOTAIR, MALAT1, LUADT1 and AFAP1-AS1 et.al exert oncogenic function in NSCLC." (PMID 26840083, 2016).
tumor (continued). "In addition, many famous lncRNAs have been found to involve in gastric tumorigenesis and progression, such as HOTAIR, H19, MEG3, HOXAAS2 and KRT7-AS, also have functions in another type of tumor." (PMID 27637083, 2016). "Eight (lincRNA-VLDLR, MEG9, H19 antisense, ncR-uPAR, NEAT1 (family), LUST, UM9-5, and HOTAIR) were significantly down-regulated in HCC tumor compared to non-tumor tissues at a significance level of p < 0.05." (PMID 26378581, 2015). "Among them, MALAT1, H19 and HOTAIR were significantly higher in plasma of tumor patients, while the other 3 lncRNAs showed no significant changes." (PMID 26096073, 2015). "Thus, we hypothesized that SNORD76, whose expression was elevated after HOTAIR knockdown, might act as a tumor suppressive gene that is suppressed by HOTAIR-mediated epigenetic modification, or an oncogene that compensates for the loss of HOTAIR, rather than a housekeeping gene in GBM." (PMID 25715874, 2015). "HOTAIR overexpression promoted and HOTAIR knockdown inhibited the xenograft tumor formation, while HOTAIR overexpression plus SETD2 overexpression did not altered the xenograft tumor growth respectively." (PMID 26172293, 2015). "The expression of HOTAIR did not correlate with nodal metastasis regardless of the scoring intensity or with other study parameters (age, tumor size and grade, expression status)." (PMID 25739705, 2015). "In this study, we first wanted to know whether the HOTAIR expression existed in human EOC tissues and in tumor bearing mice injected with SKOV3 cells." (PMID 25792974, 2015). "We also showed that HOTAIR recruiting and binding to PRC2 epigenetically represses miR34a, which controls the targets C-Met (HGF/C-Met/Snail pathway) and Snail, thus contributing to GC cell-EMT process and accelerating tumor metastasis." (PMID 26136075, 2015). "First, although in situ hybridisation for HOTAIR has been successfully established for cell lines, we were not able (despite substantial efforts; data not shown) to determine the specific subset of HOTAIR-expressing cells within the bulk tumour sample." (PMID 26497652, 2015). "In conclusion, HOTAIR is one of the well-studied PRC2 interacting lncRNAs and its expression appears to be a driving force for the acquisition of malignant properties by HCC, as well as other tumor types." (PMID 25861629, 2015). "Similarly, high HOTAIR expression was also observed in the OB-3 and SAOS-2 tumor cell lines." (PMID 36816362, 2023). "Consistent with our study, several other studies had reported that lncRNAs promote tumor angiogenesis or sunitinib resistance in RCC, including HOTAIR and lncARSR, supporting that lncRNAs may provide new targets for therapy and predictive biomarkers for anti-angiogenesis therapy response in RCC." (PMID 35562342, 2022). "HOTAIR facilitated tumorigenesis and tumor development by regulating multiple molecules (e.g., vascular endothelial growth factor (VEGF) and E-cadherin and matrix metalloproteinase-9 (MMP-9)) that were connected with epithelial-to-mesenchymal transition (EMT), tumor invasion, and metastasis." (PMID 35656022, 2022). "Interestingly, HOTAIR and MALAT1 are known to be the master regulators of tumor progression." (PMID 36387279, 2022). "The ROC curve analysis revealed that the expression levels of MEG3 and HOTAIR might discriminate GC tumor and non-tumor tissues." (PMID 35186192, 2022). "Moreover, HOTAIR can inhibit vasculogenic mimicry and cell migration in TNBC cells by sequestering miR-204, a tumor suppressor microRNA, frequently downregulated in BC, involved in angiogenesis, cell migration, as well as in the modulation of vasculogenic mimicry." (PMID 33540611, 2021).
tumor (continued). "Discrimination between HNSCC tumor and non-cancerous tissues may be further improved by combination with HOTAIR detection, whose upregulation in HNSCC was confirmed in our study." (PMID 31412811, 2019). "Notably, mast cells could directly increase the expression of HOTAIR and lead the HOTAIR-PRC2 complexes to suppress the expression of androgen receptor, thereby contributing to tumor invasion." (PMID 29368602, 2018). "Similarly, lncRNAs HOTAIR and MALAT1 are upregulated in endothelial-derived exosomes by ethanol, which might have implications for alcohol-induced tumor angiogenesis." (PMID 29678180, 2018). "In this study, we detected serum HOTAIR expression in 50 patients with ESCC (including 42 tumor resection and 8 without surgery) and 20 healthy volunteers to investigate the role of serum HOTAIR in ESCC using the quantitative real-time polymerase chain reaction (qRT-PCR) method." (PMID 28376832, 2017). "Examples of lncRNAs (H19, HOTAIR, ANRIL, MIR31HG), that recruit chromatin modifying activities and have been shown to have roles in cellular growth control and carcinogenesis, or are known to regulate the expression of tumour-suppressor genes, are presented below." (PMID 28587163, 2017). "In the mechanism of how HOTAIR contributed to NSCLC, it was thought that HOTAIR might facilitate the tumor development but not the carcinogenesis of NSCLC." (PMID 28978188, 2017). "HOTAIR also regulates BCSCs, and microarray analysis reveals HOTAIR overexpression upregualtes the genes related to stemness and EMT, such as CD44, STAT3, ALDH2, ZEB1 and VIM, but the tumor initiating frequency in vivo assay are needed to demonstrate the role of HOTAIR in regulating BCSCs further." (PMID 26349457, 2016). "This apparent discrepancy might be attributed to activation of HOTAIR expression by several metastasis-promoting signals that are aberrantly enriched in the tumor microenvironment but absent in routine cell culture." (PMID 25491133, 2014). "Moreover, of the 3 cases that did not express HOTAIR in the tumor tissue, 2 had recurrent disease." (PMID 39397388, 2025). "In addition, HOTAIR interacts with the histone-modifying complex, participating in histone methylation and demethylation, non-specifically inhibiting the expression of some tumour suppressor genes, such as PTEN and GDF15." (PMID 38203731, 2023). "Moreover, we have shown that HOTAIR exhibits a pro-oncogenic activity by modulating the cell cycle, and its main function of is to inhibit the expression of the target genes via H3K27 histone methylation and mediation of the PRC2 complex activity and to promote tumor progression." (PMID 34887871, 2021). "Additionally, our data reported that depleted HOTAIR or DNMT1 reduced the proliferation, colony formation, invasion, migration, as well as increased apoptosis rate of CML cells, while low expression of HOTAIR or decreased DNMT1 reduced the volume and weight of tumor in mice injected with CML cells." (PMID 33941772, 2021). "HOTAIR may be an oncogene and a negative prognostic factor in patients with CCA because high expression of HOTAIR was closely associated with the advanced TNM stage, larger tumor size, postoperative relapse and dismal 5-year overall survival." (PMID 30111807, 2018). "However, HOTAIR does not regulate these genes in every tumor type." (PMID 26800519, 2016). "The tumor-suppressive mechanism of ZBTB7A is not clear and the relationship of ZBTB7A to HOTAIR has never been explored." (PMID 38981872, 2024). "In the negative group (upregulated LOC285194, downregulated HOTAIR and MALAT1), a majority of patients still had a low grade tumor with only one out of five patients reporting advanced stage tumor." (PMID 34307387, 2021). "The elevated level of HOTAIR expression has been found in HCC tissues relevant to the normal tissues and to correlate with large tumor size." (PMID 33050642, 2020).
tumor (continued). "In this review we described the contribution of HOTAIR in the TME modulation, highlighting its relation with cellular and non-cellular components during tumor evolution and progression." (PMID 31072041, 2019). "HOTAIR, MALAT1, HULC, and UCA1 were similarly expressed between tumor tissues and nontumor tissues in HCC patients (P = 0.448, 0.138, 0.085, and 0.373, resp)." (PMID 26136615, 2015). "Unlike HOTAIR, the antidifferentiation noncoding RNA (ANCR) acts as a tumor suppressor." (PMID 40141248, 2025).
cardiovascular diseases (7 papers, 2020 to 2024). "HOTAIR is frequently reported as an oncogene; however, studies have also associated it with cardiovascular diseases, such as CAD and heart failure." (PMID 34064346, 2021). "HOTAIR was found to be associated with numerous cardiovascular diseases." (PMID 33294032, 2020). "In recent years, many studies have suggested that HOTAIR is involved in the occurrence and development of cardiovascular diseases." (PMID 35845040, 2022). "Many other studies showed that HOTAIR plays a key role in the development of cardiovascular diseases, highlighting specifically a cardioprotective effect partly associated with HOTAIR-miR-125 or HOTAIR-miR-1 interactions." (PMID 33540611, 2021). "HOTAIR has been proposed as a possible biomarker for cardiovascular diseases." (PMID 36421813, 2022). "Moreover, HOTAIR was reported as an antagonist of cardiovascular disease that protects against hypoxia exposure or acute myocardial ischemia by absolving miR-1 and miR-125 to inhibit apoptosis and regulate downstream genes." (PMID 34064346, 2021). "Taken together, the downregulation of HOTAIR is involved in the process of different cardiac diseases, suggesting HOTAIR may act as a protective role in cardiovascular diseases." (PMID 33294032, 2020). "More recently, reports have suggested that HOTAIR may also play a role in cardiovascular diseases." (PMID 38250607, 2024).
heart disease (6 papers, 2014 to 2023). "HOTAIR was revealed to be associated with various heart diseases in vivo." (PMID 34064346, 2021). "HOTAIR has been suggested to play roles in oncogenesis, heart disease, and nervous system functions." (PMID 36421813, 2022). "However, the underlying mechanism of HOTAIR and miR-106b-5p in heart diseases remains unclear." (PMID 32395744, 2020). "In this report, we demonstrate novel regulatory mechanisms for the lncRNA, HOTAIR, and implicate for the first time that HOTAIR plays a role in heart disease." (PMID 24788418, 2014). "More importantly, HOTAIR was closely related to heart diseases." (PMID 32395744, 2020). "However, HOTAIR has not been reported as having a role in cardiac disease." (PMID 24788418, 2014).
infection (5 papers, 2015 to 2023). The state of being infected such as from the introduction of a foreign agent such as serum, vaccine, antigenic substance or organism. "Hence, HOTAIR deregulation, under the impact of low levels of E7, could be reflective of gene expression deregulation as well, in early infection." (PMID 26152361, 2015).
head and neck tumor (3 papers, 2016 to 2019). "This study is aimed to explore the regulatory effect of lncRNA HOTAIR/miR‐148a/DLGAP1 axis on head and neck tumor (HNT) cell growth, cell mobility, and invasiveness." (PMID 29905017, 2018). "HOTAIR, although reported to be upregulated in multiple malignancies, including head and neck tumors from certain anatomic sites, was shown by our RNA-sequencing analysis to be expressed at very low levels (median cpm < 0.5) in HNSCCs overall." (PMID 27323410, 2016).
metabolic disorders (3 papers, 2016 to 2022). "Therefore, to understand the role of HOTAIR in HCV core protein-induced metabolic disorders, we examined the ROS level and NAD+/NADH ratio in pcDNA-core and si-HOTAIR co-transfected HepG2 cells." (PMID 27129296, 2016).
neurodegenerative disease (3 papers, 2022 to 2025). A disorder of the central nervous system characterized by gradual and progressive loss of neural tissue and neurologic function. "Many of these regulatory lncRNAs, such as MALAT1, NEAT1, HOTAIR, etc., are associated with different neurodegenerative diseases in humans." (PMID 36675966, 2022). "Dysregulated lncRNAs upon WS treatment included BACE1-AS, MALAT1, SNHG1, HOTAIR, MEG3, BDNF-AS, and SHANK2-AS1 which are potential biomarkers in several neurodegenerative diseases." (PMID 40928594, 2025). "Further, the authors summarize the roles of HOTAIR in the pathogeneses of other neuronal disorders, including traumatic brain injury (TBI), psychiatric conditions, and neurodegenerative diseases." (PMID 38366205, 2024).
benign tumors (2 papers, 2016 to 2020). "The analysis revealed that HOTAIR expression levels were significantly increased in metastatic CRPC (mCRPC) compared to those in localized PCa and benign tumors." (PMID 32657763, 2020).
endocrine disorders (2 papers, 2020 to 2023). "By demonstrating that HOTAIR up‐regulated the expression of IGF1 via competitive binding to miR‐130a in the rat models of PCOS, we provide insight into the mechanisms underlying the promotion effect of up‐regulated HOTAIR expression in the endocrine disorders and granulosa cell apoptosis." (PMID 31733099, 2020). "The mechanism by which HOTAIR affects ovarian function is that HOTAIR upregulates the expression of IGF1 by competitively binding to miR-130a, thereby aggravating endocrine disorders and granulosa cell apoptosis." (PMID 36845376, 2023). "We show that HOTAIR up‐regulates the expression of IGF1 and aggravates the endocrine disorders and granulosa cell apoptosis through competitive binding to miR‐130a in rat models of PCOS." (PMID 31733099, 2020).
gastrointestinal tumors (2 papers, 2021 to 2023). "Though many studies have reported that HOTAIR plays an important role in digestive system tumors, the literature lacks an updated systematic analysis and summary." (PMID 36924407, 2023). "Meanwhile, we integrated the gene matrix of six major types of Asian patients with gastrointestinal tumors in the TCGA database and found HOTAIR was closely related to the following pathways through the lncRNA–mRNA coexpression network." (PMID 36924407, 2023). "The lncRNA HOTAIR plays an important role in the formation and progression of gastrointestinal tumors." (PMID 36924407, 2023). "The present study further confirmed the role and prognostic ability of HOTAIR in gastrointestinal tumors, demonstrated the prognostic value of HOTAIR in gastrointestinal tumors by meta-analysis, and showed the correlation between HOTAIR and protein-coding genes." (PMID 36924407, 2023). "Finally, the mechanism through which HOTAIR affects tumors of the digestive system was systematically reviewed." (PMID 36924407, 2023). "HOTAIR may play an important role in these two gastrointestinal tumors." (PMID 36924407, 2023). "Down-regulation of HOTAIR can induce apoptosis of GC cells and significantly inhibit the proliferation, invasion, and metastasis of GC cells, the same findings have been found in other gastrointestinal tumors, although the signaling pathways that may be involved are inconsistent." (PMID 36924407, 2023). "However, we also noticed that HOTAIR plays an important role in other tumors, not just gastrointestinal tumors." (PMID 36924407, 2023).
kidney disease (2 papers, 2020 to 2024). "While genetic factors, particularly polymorphisms within lncRNA genes, have been identified as contributors to an elevated risk of kidney disease, our study represents the initial report elucidating the association between HOTAIR genetic variants and the risk of CKD." (PMID 38958113, 2024).
brain disorder (1 paper, 2025). A disease affecting the brain or part of the brain. "HOTAIR is also known to be involved in developmental defects and brain disorders." (PMID 40925537, 2025).